CD4 (CD4 molecule)
Diseases named in the same sentence as CD4 in open-access papers (continued):
Sharing a sentence is not in itself a finding about the gene and the disease.
visceral leishmaniasis (continued). "In our previous work, we have shown that CD4+ T cells are capable of sensing inflammatory tissue damage–derived DAMPs via TLR7 in a murine model of visceral leishmaniasis." (PMID 37227774, 2023). "We have previously reported that activation of IRF-5 in murine IFN-γ+CD4+ T cells leads to cell death during chronic visceral leishmaniasis." (PMID 37227774, 2023). "HSC activation and enhanced monopoiesis in visceral leishmaniasis have been attributed to IFN-γ-producing CD4+ T lymphocytes being recruited to the BM." (PMID 35336108, 2022). "In the asymptomatic stage (AD) of visceral leishmaniasis, CD4+ T cells also play a role by being able to lyse infected macrophages, although the relevance of this subtype of cytotoxic activity for visceral leishmaniasis in vivo is not yet well known." (PMID 35746555, 2022). "Here, we identify type I IFNs as major upstream regulators of CD4+ T cells from visceral leishmaniasis (VL) patients." (PMID 32101732, 2020). "Together, our findings suggest that miRNAs are the master regulator of CD4+ T mediated immune response in visceral leishmaniasis." (PMID 32103111, 2020). "In visceral leishmaniasis, it was shown that L. donovani promote IL-17 and IL-22 production by T CD4+ cells from healthy volunteers and patients." (PMID 29867796, 2018). "In a study of human visceral leishmaniasis, pro-inflammatory cytokines acting on splenic macrophages had the potential to upregulate IL-27, which in turn induced IL-21 to expand IL-10+CD4+CD25−Foxp3− T cells as a mechanism of positive feedback control." (PMID 29033934, 2017). "Vaccination with NH36 DNA has proven to induce protection against murine cutaneous and visceral leishmaniasis as well as against canine VL mediated by a CD4+ T-cell-dependent interferon (IFN)-γ response." (PMID 28747911, 2017). "In mice, the NH36 induced protection against visceral leishmaniasis is mediated by a CD4+ T cell response against its C-terminal domain (F3)." (PMID 28280494, 2017). "We report elevated Blimp-1 mRNA levels in CD4+ T cells from visceral leishmaniasis (VL) patients, and demonstrate IL-12 was essential for Blimp-1 expression and Tr1 cell development in experimental VL." (PMID 26765224, 2016). "More recently, presentation of KMP-11 antigen by DCs to autologous T cells from visceral leishmaniasis patients resulted in a significant IFN-γ production by CD4+ T cells." (PMID 26581100, 2015). "In the patient with visceral leishmaniasis presented herein, the CD4/CD8 ratio was found to be higher in the different spleen compartments in comparison to the other patients." (PMID 25200768, 2014). "All HIV–co-infected patients had CD4-cell counts below 200/μL (median 108, range 23–185 CD4 cells/μL) when the diagnosis of visceral leishmaniasis was made." (PMID 12890332, 2003). "The immunity against NH36 in vaccinated mice with visceral leishmaniasis (VL) is mediated by a Th1 CD4+ T cell response against its C-terminal moiety, the F3 domain, and is correlated to a strong secretion of TNF-α and an enhanced intradermal response to the leishmanial antigen." (PMID 31024556, 2019). "In visceral leishmaniasis, NKT cells seem to have a dual behaviour, depending on their subset: CD4+NKT cells show a pathogenic activity and tend to accumulate at the infection site, while CD8+NKT cells may be protective when in contact with the target cells." (PMID 28468680, 2017). "The observed anti-inflammatory activity of Ole through repression of IL-1β gene seems to be very important in the first steps of experimental visceral leishmaniasis, since IL-1β was found to be in greater necessity for CD4+ polarization to the Th2 phenotype than IL-1α." (PMID 27501956, 2016). "In the last decade when the number of visceral leishmaniasis in immunocompromised patients has been increasing, our data presented herein offered a novel insight into the possibly involvement of CD4+Foxp3+ Tregs in persistent L. donovani infection in the liver of immunodeficient hosts." (PMID 22928057, 2012).
visceral leishmaniasis (continued). "Considering that TREC copy numbers were accompanied by maintenance of low absolute CD4+ T-cell counts in relapsing-VL/HIV and correlated negatively with the number of relapses, we suggest that the thymic impairment favors the loss of parasitic control and the recurrences in visceral leishmaniasis." (PMID 32508833, 2020). "Leish-111f induces increased CD4+ cells that produce IFN-γ, IL-2, and TNF-α, which confers desirable protection against visceral leishmaniasis with significant reductions in parasite loads." (PMID 35812381, 2022). "Vaccination with NH36 has proven to protect against murine cutaneous and visceral leishmaniasis and canine visceral leishmaniasis, through an IFN-γ-CD4 response." (PMID 28747911, 2017). "Immunosuppression of antigen-specific immune responses due to impairment of DC activation, and CD4+ and CD8+ T cell exhaustion has been demonstrated in visceral leishmaniasis." (PMID 25874567, 2015). "Here we studied in detail the different T cell populations activated in BALB/c mice using the DNA/MVA vaccination approach, since Th1 responses driven mainly by CD4+ and CD8+ T cells have a major role in the immunology of cutaneus and visceral leishmaniasis." (PMID 22715418, 2012). "No vaccine is currently licensed against human visceral leishmaniasis (VL), a fatal CD4+ T cell immunosupressive disease against which chemotherapy is reduced to a few toxic drugs." (PMID 40230841, 2025). "In contrast, CD3+CD4+CD56+ NKT cells have a pathogenic profile because they accumulate at the site of infection and down-regulate CD3+CD8+CD56+ NKT cells during visceral leishmaniasis, which is due to the higher expression of CCR5 by CD4+CD56+ NKT cells compared to CD8+ NKT cells." (PMID 37235324, 2023). "In human and murine models of visceral leishmaniasis, IL-4 is hardly detectable in CD4 + and CD8 + lymphocytes, which does not agree with canine findings, at least according to the results of this study." (PMID 36703227, 2023). "Recruitment of CD4+ T cells to the BM resulted in increased HSC proliferation and functional exhaustion as well as suppression of erythropoiesis in the mouse model of visceral leishmaniasis." (PMID 35336108, 2022). "Differences in the CD4+ T-cell Vβ repertoire mobilization profile of non-relapsing and relapsing visceral leishmaniasis/HIV (VL/HIV) co-infected patients." (PMID 32508833, 2020). "However, although CD4+CD25+ T cells have been related with kala-azar and patients suffering from PKDL, FoxP3-CD4+ T cells were reported to be the key source of enhanced IL-10 mRNA expression in spleen of VL patients." (PMID 26829554, 2016). "The predictors of VL relapses are absence of an increase in CD4+ T cell counts at follow-up of patients, a lack of prophylaxis, a previous history of visceral leishmaniasis, and CD4+T cell counts below 100 cells/mL at the time of primary VL diagnosis." (PMID 25233461, 2014). "In addition, those with American visceral leishmaniasis, with profound immune suppression before HAART, can present low CD4+ T cell counts and higher proportion of activated T lymphocytes even when HIV viral load is suppressed under HAART." (PMID 23840403, 2013). "The results of this systematic review suggest there are identifiable predictive factors of VL relapse, such as previous episodes of VL relapse and lack of recovery of CD4+ lymphocyte numbers after primary visceral leishmaniasis." (PMID 21666786, 2011). "Similarly, in treated or asymptomatic visceral leishmaniasis, incomplete parasite clearance, particularly in the liver, may promote posttreatment DTH conversion through the gradual reactivation of CD4+/Th1-type immune response." (PMID 40764931, 2025). "As previously reported and supported by our findings, circulating CD4+ and CD8+ T cells from CL patients demonstrated higher expression of CD57 as compared to healthy controls, and this was also observed in T cells from the lesions of CL patients or during visceral leishmaniasis." (PMID 30662437, 2018).
visceral leishmaniasis (continued). "In comparison with the spleens of the other two patients without visceral leishmaniasis, an increase was observed in the CD4/CD8 ratio and in the number of IL-10- and FoxP3-producing cells, while the number of IL-17-producing cells was lower in the spleen of the patient with visceral leishmaniasis." (PMID 25200768, 2014).
emphysema (62 papers, 2004 to 2026). "From these results, it was assumed that ICOS-mediated CD4+ T cell activation exacerbated lung dysfunctions such as geriatric emphysema that was a risk predisposition for ICI-induced pneumonitis." (PMID 40198121, 2025). "Immune cells such as CD8+, CD4+, and T helper cells are activated and increase in response to the deterioration associated with emphysema and respiratory restriction." (PMID 36678340, 2023). "This reflects the findings in our study, in which the increase in spleen CD4+ lymphocytes upon hUC-MSC administration was associated with an improvement in emphysema." (PMID 36012176, 2022). "Depletion of either CD4+ or CD8+ T lymphocytes reduced the severity of emphysema in SIgA-deficient mice, indicating that adaptive immune activation contributes to progressive lung destruction." (PMID 32968197, 2021). "The loss of lung function in patients with COPD and emphysema is associated with a high percentage of CD4+ and CD8+ T lymphocytes that express receptors CCR5 and CXCR3, but not CCR3 or CCR4 (both markers of T helper one cells)." (PMID 33953665, 2021). "One study which set out to determine the relationship between plasma CD4/CD8 ratio and lung abnormality found that low CD4/CD8 ratio (<0.4) associated with increased emphysema (>10% involvement)." (PMID 31830103, 2019). "We also compared emphysema risk in subjects in the lowest CD4/CD8 ratio category (<0.4) to the remaining patients." (PMID 28122034, 2017). "Associations between CD4/CD8 ratio category (relative to ratio>1.0) with emphysema and airflow obstruction in logistic regression models." (PMID 28122034, 2017). "Low CD4/CD8 ratio was associated with >10% emphysema in multivariable models, adjusting for risk factors including smoking, current and nadir CD4 count and HIV RNA level." (PMID 28122034, 2017). "This has shed light on the participation of auto-immunity contributing to the overall pathogenesis of emphysema through anti-endothelial cell antibodies and pathogenic CD4+ T lymphocytes." (PMID 23720629, 2013). "Using emphysema as the main hallmark of smoking-induced lung damage, peripheral blood CD4+ T cell immune responses to elastin consistently discriminated those with and without disease over 2 years of follow-up." (PMID 22969766, 2012). "This suggested that severe emphysema is associated with inflammation involving T lymphocytes that are composed of oligoclonal CD4+ T cells." (PMID 21162738, 2010). "In E-COPD, more interactions between different subsets of T cells via CCL signaling suggest that emphysema-associated CD4 T cells might be more autonomous and possess autoreactive properties." (PMID 40993192, 2025). "Hypomethylation of the perforin gene promoter in CD4 + T cells, inflammation and oxidative stress, might be involved in alveolar septal cell apoptosis associated with emphysema in rats." (PMID 37880804, 2023). "The association between CD4/CD8 ratio with emphysema in HIV suggests that HIV-specific inflammatory pathways may be involved in the development or progression of emphysema, however, this will require further study." (PMID 28122034, 2017). "Our results suggest that the CD4/CD8 is associated with emphysema both as a continuous measure and at a threshold ratio <0.4, but these analyses were not intended to suggest that a ratio of 0.4 is optimal for defining HIV+ patients at highest risk for chronic diseases such as emphysema." (PMID 28122034, 2017). "In this study, we sought to determine whether a decreased CD4/CD8 ratio was associated with emphysema and other pulmonary function markers of COPD." (PMID 28122034, 2017). "In adjusted models, a decrease in ratio of 1.0 (i.e. a decrease in CD4/CD8 ratio from 1.5 to 0.5) was associated with 4.1 (95% CI 1.5–12) times the odds of emphysema and remained statistically significant when current CD4 and HIV viral load were added to the model (OR 4.6, 95% CI 1.2–17)." (PMID 28122034, 2017).
emphysema (continued). "This expansion was significantly blunted upon pre-treatment with pristane, suggesting that this T cell subset may be the pathogenic CD4+ T cell subset in this immune model of emphysema." (PMID 21162738, 2010). "However, whether NR3C1+ CD4 T cells are protective or pathogenic in human emphysema and COPD merits further investigation in experimental and clinical studies (Graphic Abstract)." (PMID 40993192, 2025). "In a logistic regression model adjusted for age, sex, ethnicity, smoking status, BMI and CD4 nadir, elevated TNFα (adjusted odds ratio (aOR): 1.78 [95%CI: 1.14-2.76], p=0.011) and IL-1β (aOR: 1.81 [95%CI: 1.16-2.81], p=0.009) were independently associated with emphysema." (PMID 33936110, 2021). "Regardless, the CD4/CD8 ratio may be a useful marker of risk of emphysema." (PMID 28122034, 2017). "We found that CD4 T cells in emphysema exhibited an activated transcriptomic profile indicative of heightened metabolism, augmented cytokine signaling, and enhanced inflammatory response." (PMID 40993192, 2025). "In the present study, we found that the relative abundance of CXCR6High effector memory CD4 T cells positively correlates with a higher predicted %FEV1 in the emphysema cohort." (PMID 40993192, 2025). "In young mice, lung pathology inversely correlated with SCAT levels of Tnfa, Mx1 (epithelial lesions), and Cd4 (emphysema)." (PMID 41145556, 2025). "Specifically, chronic tobacco exposure was shown to promote Tim3 expression in CD4+ T cells in the lungs of emphysema mice." (PMID 39555065, 2024). "Paralleling our observations in human COPD and emphysema, mice with CS- or nCB-induced emphysema exhibited reduced expression levels of pri-Mirlet7b/c2 and pri-Mirlet7a1/f1/d transcripts in the lung and from isolated lung CD4+ and CD8+ T cells." (PMID 38722677, 2024). "In this study, we found that the expression of Tim3 in CD4+ T cells of emphysema mice exerts an inhibitory effect on IFN-γ+ CD4+ T cells (Th1) within the lung microenvironment." (PMID 39555065, 2024). "A previous study of MSC administration in patients with severe emphysema also reported an increase in CD4+ lymphocytes." (PMID 36012176, 2022). "To assess the immunologic functions of emphysema-affected organs, we compared the numbers of CD4+ and CD8+ T-cell populations in the blood, lung, and MLNs of air-exposed and pulmonary emphysema mice via flow cytometry analysis first." (PMID 36052717, 2022). "Indeed, in explorative analyses using visual emphysema as the dependent outcome, we did find an independent association between a low CD4/CD8 ratio (<0.4) and emphysema, suggesting that residual immune activation may be involved in the pathogenesis of more severe emphysema rather than the mild." (PMID 33936110, 2021). "In explorative analyses, also using visual emphysema as the dependent outcome, we found an independent association between a low CD4/CD8 ratio <0.4 and emphysema (aOR: 3.71 [95%CI: 1.27-10.82], p=0.016)." (PMID 33936110, 2021). "By histological analysis, pIgR−/− mice treated with CD4-depleting antibodies had reduced emphysema and small airway wall thickening compared to pIgR−/− mice treated with isotype control." (PMID 32968197, 2021). "The mice fed FMT and a high-fiber diet showed reduced production of CD4+CD25+Foxp3+ T cells compared with emphysema mice, suggesting a correlation between inflammatory symptoms and Treg cell number." (PMID 32681029, 2020). "The results of univariate analysis revealed that four parameters, namely subcutaneous/mediastinal emphysema, CD4+/8+ ratio, and CRP and serum ferritin levels, were significantly different between the responsive and non-responsive groups." (PMID 31781564, 2019). "We determined the association between CD4/CD8 ratio and emphysema, and the association between CD4/CD8 ratio and pulmonary function markers of COPD." (PMID 28122034, 2017).